CTNNB1 (catenin beta 1)
Diseases named in the same sentence as CTNNB1 in open-access papers (continued):
Sharing a sentence is not in itself a finding about the gene and the disease.
craniopharyngioma (18 papers, 2017 to 2024). A benign, partly cystic, epithelial tumor of the sellar region, presumably derived from Rathke pouch epithelium. "Current research on intelligent diagnosis methods focuses on predicting preoperative craniopharyngioma invasiveness, CTNNB1 and BRAF mutations, and postoperative prognosis." (PMID 39061172, 2024). "In line with this knowledge, both adamantinomatous craniopharyngiomas profiled here (P7708_123T, P7708_126T) displayed classical mutations in exon 3 of CTNNB1." (PMID 37221626, 2023). "Since CTNNB1 mutation has been proved to be related to tumor recurrence, the prediction of CTNNB1 mutation in craniopharyngioma can facilitate surgical treatment and reduce postoperative recurrence rates with molecular targeted drugs." (PMID 35069406, 2021). "BRAF and CTNNB1 mutations are found to be strongly correlated with the pathological subtypes of craniopharyngiomas, which means the diagnosis of pathological subtypes and gene mutations has great significance for the effective adjuvant targeted therapy." (PMID 35069406, 2021). "The expression pattern was nuclear and occasionally cytoplasmic in craniopharyngiomas that harbour known genetic mutations in CTNNB1 or BRAF and was located to well-characterised tumour compartments known to express progenitor markers." (PMID 30139767, 2019). "Frequent somatic mutations of BRAF and CTNNB1 were identified in both histological subtypes of craniopharyngioma (adamantinomatous and papillary) which shed light on target therapy to cure this oncogenic disease." (PMID 30616515, 2019). "The aim of this study was to investigate the noninvasive MRI-based radiomics diagnosis to detect BRAF and CTNNB1 mutations in craniopharyngioma patients." (PMID 30616515, 2019). "In this study, we intended to propose an effective noninvasive radiomics models for the estimation of BRAF and CTNNB1 mutations in craniopharyngiomas." (PMID 30616515, 2019). "This study provides evidence that somatic loss of APC can lead to sporadic craniopharyngioma formation and may comprise a subset of adamantinomatous craniopharyngiomas that are otherwise wildtype for CTNNB1." (PMID 34549183, 2021). "To further explore the presence of copy number changes in craniopharyngioma, we explored a WGS dataset of 70 samples from 67 cases with confirmed CTNNB1 mutation, and/or methylation classification as ACP from CBTN." (PMID 39127699, 2024). "Previous craniopharyngioma sequencing studies have only focused on either codon hotspot mutations in BRAF and CTNNB1 or evaluations that were limited to 23- or 46-gene panels." (PMID 31712784, 2019). "In adamantinomatous craniopharyngiomas that are wildtype for CTNNB1 in targeted screens, APC sequencing may be considered." (PMID 34549183, 2021). "Additional genetic studies are needed to determine whether significant biological differences exist in APC- vs CTNNB1-driven craniopharyngiomas that may guide further clinical decision making and development of target therapies." (PMID 34549183, 2021). "BRAF V600E mutation and wild-type in craniopharyngiomas are discriminated with an AUC curve of 0.92 and ACC of 0.94 using two radiomics features while CTNNB1 mutation and wild-type in craniopharyngiomas are distinguished with an AUC curve of 0.95 and ACC of 0.91 based on three radiomics features." (PMID 30616515, 2019). "Molecular genetic research recently revealed that adamantinomatous craniopharyngioma has a CTNNB1 mutation but no BRAF V600E mutation, and papillary craniopharyngioma has a BRAF V600E mutation but no CTNNB1 mutation." (PMID 36913010, 2023).
craniopharyngioma (continued). "In contrast, only a few reports of craniopharyngiomas, arising from complete loss of APC through a germline and a second-hit somatic mutation and in the absence of CTNNB1 mutations, have been reported to date." (PMID 34549183, 2021).
adrenocortical carcinomas (16 papers, 2013 to 2025). "Several malignancies, such as endometrial carcinoma, hepatocellular carcinoma, and adrenocortical carcinoma, involve CTNNB1 genetic mutations that encode β-catenin." (PMID 38269250, 2023). "In this context, we asked whether FGFR2-expression is also present in adrenocortical carcinomas and if it is associated with the mutational status of CTNNB1 and clinical characteristics." (PMID 32522271, 2020). "A Pan‐Cancer analysis of 10 100 nonhypermutated cancers across 31 common cancer types from TCGA revealed that while CTNNB1 exon 3 mutations were present at 15–20% of liver, uterine, and adrenocortical carcinomas, mutations affecting CTNNB1 exon 3 are rare in other cancer types (< 3%)." (PMID 30972907, 2019). "PNU-74654 also significantly decreased cell proliferation, increased early and late apoptosis and impaired CTNNB1/β-catenin expression in an adrenocortical cancer cell model." (PMID 35723395, 2022). "As reported, CTNNB1 could affect autophagy in glioblastoma, and cell autophagy was related to the tumor microenvironment and was also involved in adrenocortical carcinomas." (PMID 32211321, 2020). "Adrenocortical carcinoma (ACC) is a rare malignancy, and CTNNB1 is frequently mutated in ACC." (PMID 29532999, 2018). "For instance, the MDM2 inhibitor nutlin-3a could selectively reduce growth of CTNNB1-mutated adrenocortical cancer cells, but not of cells with wild-type CTNNB1." (PMID 35327645, 2022). "Previous work implying Wnt/β-catenin pathway activation in immune cell exclusion has relied on gene expression signatures and focused on the relationship between CTNNB1 expression and CD8+ T cell infiltration in adrenocortical carcinoma." (PMID 40130164, 2025). "In adrenocortical cancer, PNU-74654 treatment prevented the binding of TCF to β-catenin and decreased CTNNB1 mRNA expression and nuclear β-catenin accumulation, thereby promoting apoptosis cells, reducing cell viability, and impairing adrenal steroid secretion." (PMID 37763649, 2023).
metastatic disease (16 papers, 2014 to 2025). "A large recent study of mutations in metastatic tumors also reported low CTNNB1 mutation prevalences for most forms of cancer studied." (PMID 29156750, 2017). "Our OS analysis suggests that APC/CTNNB1 somatic mutations may have some role in regional metastatic and, even more so, in distant metastatic disease." (PMID 34986841, 2022). "We detected that CTNNB1 mutations presented throughout all patients studied (100%), and a higher count of SNPs was particularly detected in patients with older age, larger tumor, and metastatic disease." (PMID 28054945, 2017). "Next-generation sequencing showed that the primary and lung metastatic tumors shared 4 mutations: PTEN (p.P248Lfs*8), CTNNB1 (p.D32A), BCOR (p.N1425S) and CBL (p.S439N)." (PMID 37328769, 2023). "Dysregulated PI3K/AKT and WNT/CTNNB1 signaling in the development and progression of metastatic tumor is mediated via a direct inhibition of beta-catenin degradation following the inhibition of GSK3beta." (PMID 27281609, 2016). "The COL5A1 mutation was absent in the metastatic tumor population (1MT2), while the CTNNB1 mutation was present exclusively in the metastatic tumor population." (PMID 40004220, 2025). "In addition to CTNNB1‐activating mutations, we found inactivating mutations of epigenetic regulators (KDM6A, TET1, BAP1) associated with metastatic disease." (PMID 30306561, 2019). "The low prevalence of CDH1 or CTNNB1 mutations in primary carcinomas suggested that mutations in these genes likely did not play much of a role in any metastatic disease that developed from these tumors." (PMID 29156750, 2017). "Among patients with T3 stage tumors, we discovered that CTNNB1 and ZNF217 mutations were mainly present in patients who were absent of metastatic disease." (PMID 36439454, 2022).
cervical cancer (15 papers, 2015 to 2025). A primary or metastatic malignant neoplasm involving the cervix. "However, in cervical cancer tissue or cancer-derived cell lines, mutations in Wnt pathway members, such as CTNNB1, have rarely been detected." (PMID 32758292, 2020). "For instance, further studies could focus on the genetic mutations and epigenetic alterations of CTNNB1 in cervical cancer, the relationship between other HR-HPV oncoproteins or different HPV subtypes, and β-catenin, the precise biomolecules-β-catenin binding mechanisms." (PMID 32758292, 2020). "In our previous study, we performed bioinformatic analysis of data from The Cancer Genome Atlas (TCGA) database and showed that the mRNA level of PDK1 was positively correlated with the expression of CTNNB1 in cervical cancer tissue." (PMID 38733179, 2024). "The expression of CTNNB1 (also known as catenin beta 1 or β-catenin) is directly upregulated by SALL4 in cervical cancer cells." (PMID 38584262, 2024). "We then transfected HeLa cells with a CTNNB1 overexpression plasmid to establish WNT/β‐catenin‐activated cervical cancer cells and used WNT signaling pathway inhibitor iCRT‐3 to inhibit WNT signaling in SiHa cells." (PMID 38733179, 2024). "Actinomycin D (Act D, 5 μM) was used to suppress the transcription of genes in cervical cancer cells, and the decrease in CTNNB1 mRNA levels was detected by RT–qPCR." (PMID 38733179, 2024). "We posit that occasional variations in CTNNB1 accompany β-catenin abnormal expression in cervical cancer, but it is accomplished by employing upstream β-catenin regulators." (PMID 32758292, 2020). "Chromatin remodeling genes ARID1A and ARID5B, WNT signaling regulator CTNNB1, and the negative regulator of PI3K signaling PTEN, were among the notable genes significantly more mutated in HPV-inactive cervical cancers." (PMID 28077784, 2017). "We showed that one or more somatic mutations occurred in 36% of cervical carcinomas, most of them in PIK3CA (24%), followed by KRAS (4%), CTNNB1 (3%), and PPP2R1A (3%)." (PMID 26197069, 2015). "We proved that the Wnt agonist CHIR-99021 and overexpression of CTNNB1 could upregulate the expression of TCF7L2 in cervical cancer cells and 293T cells." (PMID 34489551, 2021). "The LTM pathway, which regulates immune cell trafficking across the endothelial barrier, is disrupted in HPV-positive cervical cancer due to the reduced expression of key genes such as HSPA5, CTNNB1, and NPM1." (PMID 41465546, 2025). "This study provides novel insights into HPV-driven immune evasion in cervical cancer, identifying key immune-related hub genes, including HSPA5, CTNNB1, and NPM1, which are downregulated in HPV-positive tumors." (PMID 41465546, 2025). "And the relationship between the mRNA expression of CTNNB1 and PDK1 was further confirmed in our local cervical cancer tissue specimens." (PMID 38733179, 2024). "In further studies, western blot and RT-PCR demonstrated that overexpression of TCF7L2 upregulated LGR6 expression in cervical cancer cells at both the protein and mRNA levels, implying that TCF7L2 and β-catenin (CTNNB1) are upstream regulators of LGR6." (PMID 34489551, 2021). "Targeting key genes in the LTM pathway, such as HSPA5 and CTNNB1, could offer novel approaches to enhance immune cell infiltration and restore immune surveillance in HPV-positive cervical cancer." (PMID 41465546, 2025). "Our study corroborates these findings by revealing the downregulation of immune-related hub genes such as HSPA90AA1, CTNNB1, and HIF1A in HPV-positive cervical cancer, which could impair immune cell infiltration and contribute to immune escape." (PMID 41465546, 2025).
cervical cancer (continued). "Moreover, the RT–qPCR results indicated that the mRNA expression levels of NEAT1 in cervical cancer tissue were positively correlated with the expression of PDK1 and CTNNB1." (PMID 38733179, 2024). "Furthermore, the upregulation of CTNNB1, MYC, SOX2, and OCT4 in LGR6high cervical cancer cells was further validated by the RT-PCR assay in vitro." (PMID 34489551, 2021). "Interestingly, consistent with LGR6, TCF7L2, CTNNB1, MYC, and POU5F1 were all related to the poor prognosis of cervical cancer." (PMID 34489551, 2021). "Although the identified immune-related hub genes (HSP90AA1, CTNNB1, NPM1, HSPA5, and HIF1A) were significantly downregulated in HPV-positive cervical cancer, none of them demonstrated a statistically significant correlation with overall survival in the TCGA-CESC cohort." (PMID 41465546, 2025). "However, in this study, the expression of CSNK1A1 in cervical cancer tissue was significantly higher than it was in CIN tissue, but the expression of CTNNB1 in CIN and SCC tissues was not significantly different." (PMID 32993576, 2020).
fibromatosis (15 papers, 2010 to 2025). A poorly circumscribed neoplasm arising from the soft tissues. "The diagnosis of fibromatosis can be supported by positive nuclear staining with β-catenin or molecular genetic studies indicating CTNNB1 mutations." (PMID 40308488, 2025). "In a study on 101 patients with aggressive fibromatosis, there were 17 recurrences after 41 months, with a cumulative 5-year recurrence rate of 22.8%, and the CTNNB1 mutation was found in 76 patients." (PMID 39049011, 2024). "Sporadic cases of fibromatosis are commonly liked to mutations in CTNNB1, the gene for beta-catenin." (PMID 20634933, 2010). "However, in aggressive fibromatosis the CTNNB1 gene encoding the β-catenin protein is frequently mutated." (PMID 35454175, 2022). "Additional future perspectives also lie in identifying different molecular mechanisms to correlate with tumour biology and tumour behaviour in fibromatosis patients, including the role of different CTNNB1 subtypes." (PMID 35842681, 2022). "Three embryonal rhabdomyosarcomas harboured alterations in FGFR4 whilst the two aggressive fibromatosis and an embryonal RMS had CTNNB1 mutations." (PMID 33916788, 2021). "CTNNB1 regulated cell growth and adhesion and was predictive for recurrence in aggressive fibromatosis." (PMID 33488678, 2020). "Aside from the CTNNB1 and adenomatous polyposis coli (APC) mutations, the genetic profile of pediatric aggressive fibromatosis (AF) has remained poorly characterized." (PMID 27062580, 2016). "Similarly, fibromatosis also lacks ALK expression and is commonly associated with abnormal nuclear accumulation of β-catenin due to mutations in the CTNNB1 gene." (PMID 41179654, 2025). "The two entities are also different at the molecular level, with exon 3 CTNNB1 mutations being highly specific for desmoid type fibromatosis among spindle cell lesions of the breast, and APC mutations also being relatively common in fibromatosis." (PMID 34830849, 2021). "LRRK2 and CTNNB1 were also reported to interact with the Wnt pathway in fibromatosis." (PMID 31178673, 2019).
microcephaly (15 papers, 2015 to 2025). A congenital or acquired developmental disorder in which the circumference of the head is smaller than normal for the person's age and sex. "CTNNB1 (encoding β-catenin) is an ASD risk gene, with loss-of-function mutations in CTNNB1 can cause microcephaly and loss of function mutations to genes that antagonize β-catenin can result in macrocephaly." (PMID 40548072, 2025). "The child had dysmorphic features, microcephaly, hypotonia, polydactyly, retinal detachment, and neurodevelopmental disorder, with a de novo mutation of CTNNB1 c.1603C > T, p.R535X." (PMID 33425807, 2020). "We report a case of an 11-year-old boy with a de novo nonsense mutation in CTNNB1 who presented with mild ID, ataxia, spastic paraplegia, mild microcephaly and dysmorphic features." (PMID 26968164, 2016). "Several de novo mutations have also been identified in other genes mutated in microcephaly (i.e. CTNNB1 and TUBA1A) and in primary lymphedema, such as SOX18, FOXC2 and VEGFR3." (PMID 25934493, 2015). "Catenin beta 1 (CTNNB1) is also an uncommon cause of microcephaly." (PMID 36411543, 2022). "The proband described by this study presented with a phenotype that falls at the severe syndromic end of this disease spectrum, including microcephaly and neurodevelopmental delay, likely due to the demonstrated deleterious effect of the CTNNB1 c.884C>G; p.(Ala295Gly) homozygous variant." (PMID 35246174, 2022). "Peripheral spasticity, microcephaly, and central hypotonia are highlighted as CTNNB1 mutations." (PMID 34659661, 2021). "Previous studies have found that patients with CTNNB1 gene mutation may have other clinical manifestation such as microcephaly, abnormal facial features, motor and language delays, and mild visual defects." (PMID 30929091, 2019). "Phenotypic characteristics of CTNNB1 mutation patients include ID, postnatal microcephaly, mild craniofacial particularities, and neurological disorders such as peripheral hypertonia, motor, and language development delay (Online Mendelian Inheritance in Man, OMIM# 615075)." (PMID 30929091, 2019). "In contrast, the heatmap for CTNNB1 illustrates a more tightly defined range of phenotypic features, demonstrating a severe early onset neurodevelopmental disorder with postnatal onset microcephaly." (PMID 39822267, 2024). "Of the seven patients with CTNNB1‐related NEDSDV we report here, all had microcephaly and developmental delay, five had truncal hypotonia, and four had spastic diplegia, as would be expected given the cardinal features of the condition." (PMID 33350591, 2021).